IL21 (interleukin 21)
Diseases named in the same sentence as IL21 in open-access papers (continued):
Sharing a sentence is not in itself a finding about the gene and the disease.
autoimmune disease (continued). "Previously, a major barrier to leveraging IL-21 therapeutically was the possibility of inducing autoimmune disease." (PMID 37339051, 2023). "This information suggests a possible role of IL-21, as a strong promoter of inflammation, in developing the pathogenesis of autoimmune diseases such as SLE and RA." (PMID 37107636, 2023). "Of particular interest, elevation of IL-21 has been reported in autoimmune diseases including celiac disease (CD), rheumatoid arthritis (RA), and systemic lupus erythematous (SLE)." (PMID 35269395, 2022). "Modulating the IL-21/IL-21R signaling pathway is currently the focus of autoimmune disease treatment." (PMID 36293075, 2022). "Blockade of IL-4 and IL-21 driven JAK/STAT pathways serves as a specific therapeutic approach to eliminate autoreactive B cells in the patients with autoimmune diseases." (PMID 35911775, 2022). "One limitation is the use of PBMCs from healthy adults, which have a lower absolute quantity of autoimmune disease-specific T cells and cytokines, such as Tfh cells, IL-17, and IL-21, compared to PBMCs from adults with an autoimmune disease." (PMID 35265152, 2022). "IL‐21 induces inhibitor of differentiation 2 and leads to complete abrogation of anaphylaxis in mice, but also plays a role in development of autoimmune diseases such as type 1 diabetes." (PMID 34873877, 2022). "IL-21 is required for many fundamental immune processes and contributes to the development of autoimmune diseases." (PMID 35503415, 2022). "Taken together, these data suggest that IL-21 is a potential therapeutic target in a wide range of autoimmune diseases." (PMID 35503415, 2022). "Despite the normal functions, IL-4 and IL-21 are highly involved in the progression of autoimmune diseases." (PMID 35911775, 2022). "Although trials of several anti–IL-21 monoclonal antibodies for autoimmune diseases have been conducted, the only completed phase II trial is of treatment combined with liraglutide in patients newly diagnosed with T1D (ClinicalTrials.gov NCT02443155)." (PMID 35503415, 2022). "Interleukins 4 (IL-4) and 21 (IL-21) belong to the common gamma chain cytokine family which are highly involved in the progression of autoimmune diseases." (PMID 35911775, 2022). "More importantly, increased serum IL-21 levels have been reported in patients with autoimmune diseases, including systemic lupus erythematosus, rheumatoid arthritis, multiple sclerosis, and Sjögren’s syndrome, diseases that have been linked to EBV infection." (PMID 35482424, 2022). "Instead, the more selective monoclonal antibodies targeting IL-4 and IL-21 were developed and tested in patients with autoimmune diseases, which showed significant clinical efficacies." (PMID 35911775, 2022). "This study on SLE linked IL-21 to Tfh-mediated regulation of B cells, providing important evidence that Tfh cells can induce CD19+CD5+CD1dhiBregs, possibly through IL-21 in autoimmune diseases." (PMID 33841422, 2021). "Interleukin-21 has been suggested to be involved in the induction of several autoimmune diseases and has also been correlated with both MS severity and progression." (PMID 34707149, 2021). "Clinical studies on the effects of IL-21 in solid tumors have produced beneficial results in treatment; yet, on the other hand, IL-21 promotes autoimmune diseases." (PMID 33515210, 2021). "Elevations of IL-21 have been reported in the pathogenesis of some autoimmune diseases, including celiac disease (CD), rheumatoid arthritis (RA), and systemic lupus erythematous (SLE)." (PMID 33562074, 2021). "IL-21, a pro-inflammatory cytokine elevated in several autoimmune disorders, shows increased plasma levels in AA, as well as IL-21-producing CD4+ T cells in the BM that are positively correlated with Th17 frequency and negatively correlated with Treg number." (PMID 33445786, 2021). "It was found to decrease the severity of autoimmune diseases in experimental animals through its interaction with IL-21." (PMID 33628507, 2021).
autoimmune disease (continued). "IL-21 is a pleiotropic cytokine, which is related to autoimmune diseases, allergies, and inflammatory diseases." (PMID 33588839, 2021). "Recently, Th17 related cytokines such as IL-1β, IL-6, IL-17, IL-21, IL-22, and IL-23 play crucial roles in the pathogenesis of many diseases, including inflammatory diseases, autoimmune diseases, and cancers." (PMID 32252668, 2020). "Overexpression of IL-21 is a feature of many inflammatory and autoimmune disorders, including Sjögren’s syndrome, systemic lupus erythematosus, type 1 diabetes, multiple sclerosis, rheumatoid arthritis, and inflammatory bowel disease." (PMID 30682117, 2019). "The previous studies have demonstrated that the levels of both IL-21 and IL-6 are significantly associated with the frequency of TFH cells in the autoimmune diseases." (PMID 31875006, 2019). "IL21 is mainly secreted by Th17 cells in autoimmune diseases, and has a major role in driving terminal B-cell differentiation to plasma cells while having a major stimulatory effect on antigen-specific autoreactive T-cells." (PMID 30733517, 2019). "IL-21 expression is significantly increased in some Th17-related autoimmune diseases, such as rheumatoid arthritis, multiple sclerosis, and inflammatory bowel disease." (PMID 31440249, 2019). "Although IL-21 has been widely studied in other autoimmune diseases, the role of IL-21 is still unclear in psoriasis." (PMID 31440249, 2019). "IL21 regulates both innate and adaptive immune responses, and also exerts major effects on inflammatory responses that promote the development of autoimmune diseases and inflammatory disorders." (PMID 30036399, 2018). "Th17 cells secrete IL-17 as well as cytokines such as IL-21 and IL-22, and IL-17 can aggravate inflammatory reaction and participate in various autoimmune diseases." (PMID 30151032, 2018). "For example, high levels of IL-21 have been demonstrated to promote a range of autoimmune diseases, including multiple sclerosis, inflammatory bowel disease, and psoriasis." (PMID 30115117, 2018). "Recent reports suggest that Th17 cells, which produce IL-17A, IL-17 F, IL-21 and IL-22, not only mediate the clearance of pathogens but also promote the progression of tissue inflammation and autoimmune diseases." (PMID 28646856, 2017). "IL-17, IL-6 and IL-21 cytokines can aggravate the development of autoimmune disease by triggering inflammatory reactions." (PMID 28646856, 2017). "Recently, there is growing evidence that IL-21 leads to the pathogenesis of chronic inflammatory and autoimmune diseases due to its biological functions." (PMID 29511486, 2017). "This subtype is involved in the pathological process of tumors, host defence, infection, autoimmune diseases, and transplant rejection through the secretion of certain cytokines, such as interleukin (IL)-17A, IL-17F, IL-21, IL-22, and IL-6." (PMID 28796055, 2017). "BXSB-Yaa mice,which develop SLE-like disease, have an increased serum expression of IL-21, suggestinga possible role for IL-21 in the development of the autoimmune disease in this animalmodel." (PMID 27096200, 2016). "The combined effect of reduced TGF-β and enhanced IL-6, IL-21 cytokines influence the balance between Th17 or Treg cells in leprosy reactions as reported in the murine models and autoimmune diseases." (PMID 27035913, 2016). "In human autoimmune diseases, IL-21 appears to have the potential to exacerbate cellularprocesses that determine the course of autoimmune response." (PMID 27096200, 2016). "Elevated amounts of IL-21 have subsequently been reported in many autoimmune diseases, including type 1 diabetes, rheumatoid arthritis, systemic lupus erythematosus, Sjogren’s syndrome, inflammatory bowel diseases, and primary biliary cholangitis (PBC)." (PMID 27386263, 2016). "Several studies have demonstrated a correlation between the severity of autoimmune diseases and IL-21 levels." (PMID 27386263, 2016).
autoimmune disease (continued). "The roles of IL-21 signaling in different immune cell compartments have also been addressed in other models of autoimmune diseases." (PMID 27535236, 2016). "The dual role of IL-21 in immune regulation raised a note of caution in the use of therapeutic agents blocking the IL-21/IL-21R axis in autoimmune diseases, as also suggested by preclinical studies in murine lupus models." (PMID 25961061, 2015). "Currently, there are many on-going autoimmune disease clinical trials targeting IL-21 and its signaling pathway." (PMID 25768299, 2015). "Th17 cells synthesize IL-17A, IL-17F, IL-21, and so forth and have been demonstrated in autoimmune disease such as Sjögren's syndrome, multiple sclerosis, psoriasis, autoimmune uveitis, juvenile diabetes, rheumatoid arthritis, and Crohn's disease." (PMID 26078981, 2015). "Interleukin (IL)-21 is a key cytokine in autoimmune diseases such as systemic lupus erythematosus (SLE) by its regulation of autoantibody production and inflammatory responses." (PMID 26055806, 2015). "We chose the rs6822844 IL2-IL21 gene cluster polymorphism because of its promising character in studies on autoimmune diseases and the involvement of IL-2 and IL-21 in the rejection process." (PMID 25377634, 2014). "Our results suggest an additional mechanism, where depletion of GC B cells results in elimination of mature Tfh cells, which are the main driver for GC reaction in autoimmune diseases and are also a source of pro-inflammatory cytokines, such as IL-21." (PMID 25101629, 2014). "Interleukin-21 (IL-21) is a pleiotropic cytokine linking innate and adaptive immune responses, which has been reported to play a key role in multiple autoimmune diseases." (PMID 24944624, 2014). "Multiple studies in animal models indicate a pivotal role of IL-21 in the pathogenesis of autoimmune diseases." (PMID 23799890, 2013). "Animal and clinical studies demonstrated the dysregulations of IL-21 and IL-21R in autoimmune diseases." (PMID 23889847, 2013). "The abnormality of interleukin-21 (IL-21)-IL-21-receptor (IL-21R) system has been found in many autoimmune diseases including autoimmune thyroid diseases (AITDs)." (PMID 23889847, 2013). "Since it was reported that Th17 cells are induced by TGF-β, IL-1, IL-6, IL-21 or IL-23, antibodies targeting IL-6 or IL-23 have been considered strong candidates for the development as treatments for autoimmune diseases, including IBD and rheumatoid arthritis." (PMID 24649227, 2013). "IL-21 has pleiotropic effects on innate and adaptive immune response, and plays an important role in the development of autoimmune disease and antitumor activity." (PMID 23741351, 2013). "TCD4+ cells that secrete IL-17, Th17 cells, are pathogenic in autoimmune diseases, and their development and expansion is driven by the cytokines IL-6, TGF-beta, IL-21, IL-1, and IL-23." (PMID 22400033, 2012). "Increased IL-21 production has been reported to enhance autoantibody production in autoimmune diseases because of its capacity to induce the differentiation of B cells towards antibody secreting plasma cells." (PMID 23064011, 2012). "Accumulating evidence indicates that IL-6 can enhance Th17 cell differentiation by promoting the sequential engagement of IL-21/IL-23 pathways and that it plays a critical role in Th17-dependent autoimmune diseases." (PMID 21801431, 2011). "Interleukin-21 is required to reinforce differentiation of Th17 cells, and it plays a critical role in Th17-dependent autoimmune diseases." (PMID 21801431, 2011). "Human studies provide further evidence that the IL-21/IL-21R pathway plays a major role in the pathogenesis of autoimmune diseases, in particular in SLE." (PMID 21959034, 2011). "This 480 kB block of linkage disequilibrium includes IL2 and IL21, which are both functional candidate loci for autoimmune diseases." (PMID 22065918, 2011).
autoimmune disease (continued). "Selective neutralization of the IL21/IL21R signaling pathway is a promising approach for the treatment of a variety of autoimmune diseases." (PMID 20504348, 2010). "In view of the crucial effects of IL-17 in the pathogenesis of autoimmune diseases, including uveitis, we investigated the influence of IL-21 on IL-17 production in the EAU model." (PMID 20057909, 2009). "Studies have demonstrated that IL-21 is essential for the differentiation of Th17 cells and plays a crucial role in the pathogenesis of several autoimmune diseases." (PMID 20057909, 2009). "In this study, we explored the involvement of IL-21 in the pathogenesis of EAU, given that IL-21 acts as an essential cytokine in immune responses and plays important roles in many autoimmune diseases." (PMID 20057909, 2009). "Interleukin (IL)-21 has recently been shown to play a vital role in the development of many autoimmune diseases." (PMID 20057909, 2009). "This region harbors the interleukin 2 (IL2) and interleukin 21 (IL21) genes and was recently shown to be associated with four autoimmune diseases (Celiac disease, Type 1 diabetes, Grave's disease and Rheumatoid Arthritis)." (PMID 18369459, 2008). "Abnormal expression of interleukin-21 (IL-21) can induce a variety of autoimmune diseases." (PMID 41012511, 2025). "The first in vivo study targeting IL-21 in a lupus-prone MRL-Fas(lpr) mouse model—commonly used to study autoimmune diseases, such as lupus—was conducted more than 15 years ago, at a time when the production of IL-21 by Tfh cells had not yet been fully elucidated." (PMID 40283219, 2025). "Clinical studies involving the IL-21 signaling pathway as an intervention in the field of organ transplantation are relatively limited, but significant work has been done in the fields of autoimmune diseases and cancer immunotherapy." (PMID 40376002, 2025). "Excessive IL21 has been found in at least seven autoimmune diseases to date." (PMID 40440345, 2025). "Additionally, Th17 cells (IL-17A, IL-17F, IL-21, and IL-22) are known to play an inflammatory role in mediating autoimmune diseases.." (PMID 38685091, 2024). "Under the reflection of CD8+ T cells to chronic antigen presentation, IL-21 may be involved in driving autoimmune diseases." (PMID 38188028, 2023). "Given the importance of IL-21 for autoimmunity, blood IL-21 levels could serve as a potential biomarker of disease activity in autoimmune disorders." (PMID 37415982, 2023). "IL21 has been involved in lupus and psoriasis autoimmune diseases." (PMID 37175481, 2023). "According to the hypothesis of a bidirectionality between autoimmune diseases and AN, the role of IL-21 seems to be important also in the pathogenesis of AN." (PMID 37432371, 2023). "We speculate that blockade of IL-4 and IL-21 upregulation serves as a common strategy by repairment of the tolerance checkpoints to trigger apoptosis of autoreactive B cells during autoimmune diseases." (PMID 35911775, 2022). "Conversely, IL-21/IL-21R blockade may also have therapeutic benefits in the treatment of autoimmune diseases and inflammatory conditions." (PMID 35777300, 2022). "IL-17RB, IL-23a, IL-21, and IL-6 are significantly related to autoimmune diseases." (PMID 35358276, 2022). "Second, IL‐21-IL‐21R blockade may also have therapeutic benefit in the treatment of autoimmune diseases and inflammatory conditions." (PMID 33173427, 2020). "Similar to Tfh-like cells, which were found in SLE and other autoimmune diseases, the super-functional subset delivers effective B-cell help for IgG production in an IL-21- and CD40L-dependent manner." (PMID 32441253, 2020). "Given that both administering IL-21 (for cancer) and blocking IL-21 (for autoimmune disease) are of potential clinical interest in humans, it is important to be cognizant of possible effects on host defense of modulating levels and the actions of this cytokine." (PMID 30969166, 2019).
autoimmune disease (continued). "Indeed, the effectiveness of JAK3 inhibitors in autoimmune disease presumably at least partially relates to the inhibition of IL-21 signaling." (PMID 30969166, 2019). "Several murine models indicate a crucial role of IL-21 in the pathogenesis of autoimmune diseases." (PMID 31331400, 2019). "The importance of IL-21 has already been demonstrated in preclinical studies in autoimmune disease." (PMID 31024571, 2019). "Several studies have shown that IL-21 plays a vital role in autoimmune diseases." (PMID 31440249, 2019). "Numerous studies suggest that IL-21 plays a significant role in autoimmune disorders." (PMID 30682117, 2019). "IL-21 plays a critical role in the adaptive immune response due to its ability to stimulate B cell differentiation and antibody production, and to promote the maladaptive development of inflammatory disease and autoimmune disorders, such as type 1 diabetes." (PMID 28125737, 2017). "IL-21 imparts both autocrine and paracrine effects on lymphocytes influencing survival and differentiation and contributes to the development of inflammatory and autoimmune diseases." (PMID 31557986, 2016). "Overall, these findings combined with our own support the idea that, early in disease, high levels of Th cell-specific cytokines such as IL-21 modulate the immune system and subvert its ability to maintain self-tolerance, ultimately leading to autoimmune disease such as SLE." (PMID 26055806, 2015). "How these influences on T cell differentiation and effector function by IL-21 interact in an in vivo setting and contribute to autoimmune disease pathogenesis, especially balanced against the ability of IL-21 to promote B cell differentiation and antibody production, requires further investigation." (PMID 25652388, 2015). "This raises the possibility that similar than targeting cytokines such as TNF-α, IL-12/23, IL-17, or IL-21 blocking of IL-9 might be of potential benefit in patients with psoriasis and other Th17 cell-mediated autoimmune diseases." (PMID 23335955, 2013). "Additionally, genetic associations between different polymorphisms located within the IL2/IL21 region as well as within both IL2RA and IL2RB loci and several autoimmune diseases have also been reported." (PMID 23676143, 2013). "IL-21 has been shown to play an important role in autoimmune diseases." (PMID 23496892, 2013). "IL2 and IL21 genes are both functional candidates for autoimmune diseases as they may be involved in the regulation of T-cells responses." (PMID 22876110, 2012). "Additional lines of evidence also suggest that IL-21 may promote human autoimmune disease in general." (PMID 22030011, 2011). "Multiple murine models indicate a pivotal role of IL-21 in the pathogenesis of autoimmune diseases." (PMID 21959034, 2011). "However, the precise roles IL-21 and IL-21R in human autoimmune disease are still poorly understood." (PMID 22030011, 2011). "Since previous observations suggest that IL-21 and IL-21R may be associated with immunoglobulin production, autoantibody production, and B-lymphocyte hyperactivity, it is thought that IL-21 is involved in the pathogenesis of autoimmune disease." (PMID 22030011, 2011). "Candidate gene studies have identified single variants (not observed on GWAS) within IL-21 to be associated with autoimmune diseases including SLE, type 1 diabetes and atopic asthma." (PMID 20184734, 2010). "However, similar to STAT4, other IBD susceptibility genes such as IL23R, IL2/IL21, STAT3, and PTPN2 are associated with other autoimmune diseases." (PMID 20454450, 2010). "IL-21 has a critical role in terminal B cell differentiation to plasma cells and has recently been identified as an important component in the development of autoimmune disease." (PMID 20359360, 2010).